PPARA (peroxisome proliferator activated receptor alpha)
Diseases named in the same sentence as PPARA in open-access papers (continued):
Sharing a sentence is not in itself a finding about the gene and the disease.
metabolic disorders (continued). "Consistent with their roles in cellular fatty acid metabolism, activation of PPARs by agonists such as fibrates (PPARα) and thiazolidinediones (PPARγ) has demonstrated clinical efficacy in treating metabolic disorders in humans (9, –, 11)." (PMID 36715509, 2023). "By integrating the latest research findings, we hope to shed light on the potential therapeutic implications of targeting PPARα in the prevention and treatment of metabolic disorders." (PMID 38004166, 2023). "A report demonstrated that Z-551, a PPARα agonist ameliorates high-fat diet-induced obesity and metabolic disorders in mice, and one of the mechanisms by which it exerts its effect is by reducing ATM that ultimately suppresses AT inflammation." (PMID 36718668, 2023). "Peroxisome proliferator-activated receptor alpha (PPARα) is an interesting therapeutic target for treating metabolic disorders in the clinic, including NASH." (PMID 38034083, 2023). "Currently, metabolic diseases have already benefited from the clinical application of PPARα partial agonists, showcasing their significant therapeutic potential." (PMID 38004166, 2023). "Understanding the complex interactions between PPARα and metabolic diseases holds promise for the development of innovative therapeutic strategies and personalized medicine approaches for these devastating diseases." (PMID 38004166, 2023). "PPARα, one of them, is expressed heavily in the liver and is currently being investigated as a therapeutic target for metabolic disorders like NASH." (PMID 38034083, 2023). "In NASH model mice, the PPARα/γ dual agonist saroglitazar and the PPARα/γ/δ triple agonist lanifibranor are effective in protecting the liver from metabolic disorders and fibrosis." (PMID 37576819, 2023). "Of note, several studies have demonstrated that dual PPARα and PPARγ agonists are effective for treatment of metabolic diseases including NAFLD in ob/ob mice and rats." (PMID 36172518, 2022). "BVR-A has newly recognized roles in hepatic lipid regulation in the context of metabolic diseases, via regulation of a peroxisome proliferator activator-alpha (PPARα)-dependent pathway." (PMID 35326205, 2022). "PPARα is a ligand-activated transcription factor of clinical interest as a drug target in various metabolic disorders, which also contributes to the activity of endothelial nitric oxide synthase (eNOS) and regulates vascular tone." (PMID 33728018, 2021). "The effects of PPAR agonists currently used in clinical practice for treatment of cardiovascular and metabolic diseases, such as fibrates (mostly activating PPARα) or glitazones (mostly activating PPARγ) should be considered." (PMID 34445694, 2021). "Several different naturally available ingredients have been shown to ameliorate the NF-κB activation seen in a host of metabolic disorders through the PPARα pathway." (PMID 33147850, 2020). "Through the last decades, several members of classical agonist families such as the fibrates (PPARα), the glitazones (PPARγ), and the glitazars (PPARα/γ) have been approved for the treatment of metabolic diseases in humans." (PMID 32695150, 2020). "As partial agonists of PPARα and PPARγ, CoQ10, idebenone and other related benzoquinones have the potential to treat a variety of metabolic disorders." (PMID 30171034, 2018). "Our identification of CoQ10 and its more soluble analog idebenone as partial agonists for both PPARα and PPARγ provides new insight into PPAR molecular and genetic functions, as well as promising new reagents for treating and preventing metabolic disorders." (PMID 30171034, 2018). "Pristanic acid is one of the natural ligands of PPARα, and represents the final product of alpha-oxidation of phytanic acid that accumulates in a variety of metabolic disorders." (PMID 27434237, 2016). "Pharmacological activation of PPARα has anti-inflammatory activities in liver, adipose, and vascular tissues and PPARα agonists are proposed to be promising candidates for metabolic disorders." (PMID 25383754, 2014).
metabolic disorders (continued). "Therefore, our study identified FAM3A/PPARα axis as a novel signaling pathway that regulates metabolic disorders and balances excess lipids and IR." (PMID 41353211, 2025). "Therefore, activating the PPARα/PGC1α pathway can potentially mitigate IR and manage IR-induced metabolic diseases by enhancing mitochondrial quality." (PMID 39337550, 2024). "Using targeted and untargeted metabolomic analysis, we discovered that GPS regulated EPA and DHA to improve metabolic disorders through activation of the PPARα pathway, and L-serine and glycine to inhibit inflammation and oxidative stress through suppression of the HIF-1α pathway." (PMID 38515850, 2024). "As our understanding of PPARα expands, therapeutic approaches targeting this receptor may offer innovative perspectives for managing related metabolic diseases." (PMID 38004166, 2023). "Furthermore, some studies have reported that dietary or natural chemicals attenuate metabolic diseases through increasing the expression of PPARα." (PMID 35745260, 2022). "Ongoing work in sirtuin-targeted drug discovery may ultimately lead to the consideration of SIRT1 inhibitors as therapeutic alternatives to or amplifiers of PPARα agonists (e.g., fibrates) for metabolic disorders." (PMID 35419389, 2022). "This study establishes the unexpected role of basal autophagy for the therapeutic effects of pharmacologically targeting the nuclear receptor PPARα, which may be useful for the treatment of diverse metabolic diseases." (PMID 35203398, 2022). "In view of its function, TFEB activation, induced by nuclear receptor PPARα with currently available drugs or new molecules, might be a therapeutic target for the treatment of metabolic diseases." (PMID 36670934, 2022). "Accordingly, elevated levels of protective PUFAs might contribute to improved mitochondrial function (i.e., increased β-HAD activity and PPARα activation) to attenuate development of metabolic disease in PQQ-supplemented offspring." (PMID 35682720, 2022). "Given that PER2 also interacts with nuclear receptors including PPARα and can regulate the expression of nuclear receptor target genes involved in lipid metabolism, PER2 polymorphisms could contribute to metabolic disorder vulnerability." (PMID 35276838, 2022). "Emerging studies also suggest that the BVRα/GSKα/PPARα axis may provide an attractive therapeutic target in metabolic disease and related cardiovascular or renal conditions." (PMID 35326205, 2022). "Therefore, these computational analysis results are in agreement with the inhibition of metabolic disorders associated genes presented in this study, demonstrating that DPP is a strong PPARα agonist." (PMID 34639224, 2021). "PPARα/γ dual agonists have shown good potentials to treat metabolic diseases." (PMID 34593018, 2021). "Taken together, these results suggest that FME may improve the metabolic disorders of obese mice partly though PPARα signaling." (PMID 24705395, 2014). "Since UCP2 is a critical regulator of cellular glucose and lipid metabolism, we propose that FME may ameliorate metabolic disorders of obese mice partly though the regulation of PPARα signaling pathway." (PMID 24705395, 2014). "Due to the important functions played by the PPAR isotypes, PPARα and PPARγ have long been considered promising drug targets for human metabolic disorders as they regulate lipid and/or glucose homeostasis by controlling uptake, synthesis, storage, and clearance." (PMID 23737762, 2013). "We found that that pomelo peel extracts could prevent high-fat diet-induced metabolic disorders in C57BL/6 mice through the activation of the PPARα and GLUT4 signaling." (PMID 24147098, 2013). "However, recent studies have shown that the increase mRNA expression of PPARα and -γ also have significant therapeutic influences on the metabolic disorders." (PMID 24312343, 2013).
metabolic disorders (continued). "Since PPARα blocks the replication and production of infectious viral particles, its downregulation likely confers a replicative advantage to the virus in spite of the resulting metabolic disorders for the host cells." (PMID 23024649, 2012). "Furthermore, therapies targeting the PPARα–gut microbiome axis may offer innovative approaches for treating metabolic diseases, given the growing evidence of the gut microbiome's influence on metabolic health." (PMID 40926269, 2025). "Notably, PPARα contributes to the progression of IR-induced metabolic diseases, including T2DM." (PMID 39337550, 2024). "Additionally, a decrease in PPARα gene exhibiting protective properties against metabolic disorder and inflammation may potentiate PMMA-induced inflammation." (PMID 38564126, 2024). "Compound 222, in contrast, was the only metabolite found to be a potent dual agonist of both PPARα and PPARγ (50 μM= 2.13-fold induction; 25 μM= 1.85-fold induction; 12.5 μM= 1.42-fold induction), and its activity represents a great potential for the treatment of metabolic disorders." (PMID 37765290, 2023). "In addition to the known interactions between estrogen and PPARα transcriptional activity, sexual dimorphism of PPARα protein levels could have important implications for sex differences in the frequency of metabolic disorders and their treatment." (PMID 35419389, 2022). "Therefore, PPARα is an effective therapeutic target for the treatment of metabolic disease." (PMID 28469249, 2017). "In addition to hepatocytes, PPARα is expressed in other relevant immune cells such as dendritic cells, non-hepatic macrophages, as well as B and T lymphocytes, which can infiltrate the liver during development of metabolic disorders." (PMID 25511156, 2014). "It was proposed that fine-tuning the activity of PPARα and PPARγ, in particular, by nutritional approaches at specific time/s during the transition period might be a way to prevent and/or help the cows overcome metabolic disorders." (PMID 23737762, 2013). "In terms of metabolic disorders, nuclear receptors such as FXR, LXR, and PPARα maintain the body’s energy balance by regulating bile acid, lipid, and carbohydrate metabolism." (PMID 40650120, 2025). "The development of PPARα agonists and dual PPAR agonists offers promising strategies for treating CVD and metabolic disorders while improving patient outcomes." (PMID 40926269, 2025). "Disruption by xenobiotic chemicals can induce metabolic disorders, primarily through the activation of PPAR subtypes, notably PPARα." (PMID 39065726, 2024). "The future discovery of anti-NASH (or anti-metabolic disease) PPAR agonists will unequivocally have fundamental benefits from the in-depth functional and structural investigation of PPARα/δ/γ-LBD–ligand molecular interactions." (PMID 37627329, 2023). "Earlier studies on rabbits have shown that compounds isolated from CM fruit extract increase the expression of PPARA and PPARG receptors and indicate an important role of PPARG in the regulation of potential metabolic disorders." (PMID 35684107, 2022). "Consequently, we showed that the CLA-induced hepatic triglyceride accumulation can be rescued by small-molecule drugs targeting either PPARα or REV-ERBα with the modified circadian clock program; this may be an alternative strategy to manage the associated metabolic disorders." (PMID 34722605, 2021). "Since this induced process is closely related to triglyceride hydrolysis and ketone body production, PPARα-dependent FGF21–JMJD3 autophagy signalling emerges as an important endocrine regulator and a potential therapeutic target in metabolic disorders." (PMID 34638914, 2021). "And thus, we conclude that V9 supplementation alleviates HFD-induced metabolic disorder through upregulating the AMPK and PPARα signaling pathways." (PMID 32472368, 2020).
metabolic disorders (continued). "Therefore, on the basis of our findings we can state that RSV could act as a powerful enhancer of ATGL/FA/PPARα pathway, thus representing a valid natural tool to limit the onset and/or the exacerbation of the age-related metabolic disorders and inflammatory states." (PMID 24817795, 2014). "In vitro, FGF15/19 intervention attenuated PA‐induced metabolic disorders and lipid accumulation in mouse atrial cardiomyocytes coupled with increased inflammation and the phosphorylation of CaMKII and YAP, which was reversed by the PPARα inhibitor." (PMID 37186335, 2023). "PPARα, PPARγ, and FXR agonists are used clinically to treat lipid disorders and metabolic diseases." (PMID 37427406, 2023). "Altogether, although data on histone modifications in metabolic diseases including NAFLD and key players such as PPARα remain fragmentary, the current data already highlight the importance of histone methylation and acetylation regulation of PPARα in the development of NAFLD." (PMID 36551797, 2022). "Thus, the activation of PPARα, LXR, and SREBP-1c, and their regulation of SCD1 are potential pathways in metabolic diseases, but the mechanisms of action in some tissues (e.g., the kidneys) have not yet been elucidated." (PMID 35694255, 2022). "Overall, induction of AMPK and PPARα activity in muscle cells of OVA ADPN KI chicken egg-derived ADPN was similar to that observed for recombinant ADPN, highlighting it as a candidate drug for metabolic diseases such as T2D." (PMID 36761986, 2022). "Wenting Wan found that aqueous extract of black maca could prevent metabolic disorders by regulating the glycolysis/gluconeogenesis‐TCA cycle and PPARα signalling activation." (PMID 34136157, 2021). "Taken together, these findings suggest that PPARα may be mediating the protective effects of higher serum TBIL on a range of cardiovascular and metabolic diseases." (PMID 34117260, 2021). "Under starvation, the absence of PPARα in mouse liver leads to decreased β-oxidation activity of cell mitochondria, which is unable to fully utilize free fatty acids, resulting in liver lipid metabolism disorder and severe hepatic lipid accumulation." (PMID 40650120, 2025). "Furthermore, propolis activates PPARα in the liver to balance lipid metabolism, and its active component, caffeic acid phenethyl ester (CAPE), can upregulate PPARα and downregulate PPARγ to relieve fat accumulation and metabolic disorders." (PMID 41141253, 2025). "PPARA, PPARGC1A, and PPARGC1B, which are involved in the fatty acid oxidation of PLN-KO hiPSC-CMs, began to decline at day 30, while genes involved in glucose utilization, such as GNPNAT1, PGM3, and GFPT1, were upregulated, indicating that energy metabolism disorders began to occur." (PMID 35334215, 2022). "In addition, cardiac-restricted overexpression of PPARα developed DCM and fatty livers, indicating that cardiac metabolic remodeling could in turn induce systemic metabolic disorders." (PMID 30635067, 2019). "Current reports suggest that okra polysaccharides (OP) have therapeutic effects on metabolic diseases via the inhibition of LXR and PPAR signaling, and Astragalus polysaccharides could regulate gene expression of PPARα and its target genes to improve lipid metabolism." (PMID 28885549, 2017).
infection (108 papers, 2007 to 2026). The state of being infected such as from the introduction of a foreign agent such as serum, vaccine, antigenic substance or organism. "Interestingly, PPARA deficiency in mice is lethal in cases of infection with LPS‐producing bacteria." (PMID 35706367, 2022). "However, considering the previously stated increase in risk of infection, a dual PPARα/γ agonist would be a safer approach, especially considering both PPARγ and PPARα inhibit iNOS related ROS production." (PMID 35003101, 2021). "In contrast, 221 genes were induced by infection only in nhr-49/PPARA mutants, and thus it appeared that nhr-49/PPARA loss may be compensated by a large infection-specific response that does not normally occur in wild-type animals." (PMID 33978570, 2021). "In addition, PPARα deficiency led to excessive production of proinflammatory cytokines and chemokines after infection of the lung and macrophages." (PMID 32155958, 2020). "In this scenario, a PPARα variant allele may contribute to the modulation of infection by enhancing the accumulation of cholesterol in infected cells and by shuttling cholesterol to Leishmania parasites." (PMID 25242866, 2014). "Particularly, infection of HCV causes abnormal stimulation of PPARα." (PMID 23316217, 2012). "Our transcriptomic analysis indicates that the PPARα and peroxisome pathways are downregulated during infection, along with many metabolic pathways of hosts (such as fatty acid degradation, bile acid biosynthesis, and glycerophospholipid metabolism)." (PMID 40303088, 2024). "The impact of PPARα on S. aureus virulence was assessed in an immunocompetent skin/soft tissue (SSTI) infection model using C57BL/6 and C57BL/6 Ppara-/- mice." (PMID 38601738, 2024). "In conclusion, the hepatic PPARα metabolic response to infection is crucial to the host defense response." (PMID 36831317, 2023). "In the context of infection, PPARα has been shown to play an essential role in the hepatic metabolic response to infection." (PMID 36831317, 2023). "Gemfibrozil, a PPARα activator, reduced the in vivo Mabc load and lung inflammation during infection." (PMID 36831317, 2023). "We pretreated, as before, with PPARα agonists overnight and replaced agonist in the media following infection with MHV68 (pre/post)." (PMID 36715509, 2023). "Naringenin, a grapefruit flavonoid, suppressed HCV production by inhibiting viral particle assembly via PPARα activation, suggesting potential roles for PPARα agonists in the resolution of infection." (PMID 36831317, 2023). "We observed significant bacterial killing by wild type macrophages at 30 minutes post-infection while activation of PPARα by WY14643 significantly decreased the ability of macrophages to kill S. aureus." (PMID 35860381, 2022). "PPARα has been demonstrated in other infection and disease models to exert an anti-inflammatory or repair activity." (PMID 35860381, 2022). "A recent study reported that PPARα stimulation suppressed interferon production through modulation of reactive oxygen species (ROS) production during infection." (PMID 36409895, 2022). "PPARα was demonstrated to be protective against infection since BMDMs from PPARα−/− mice had increased M.tb growth compared to WT." (PMID 36297211, 2022). "On the other hand, the expression levels of BCL2, CDKN2A, IL-6, and PPARA remained similar in both male and female mice after infection but were significantly upregulated in male mice after infection in combination with exogenous SP-A2 (1A0) protein." (PMID 35844510, 2022). "This indicated that nhr-49/PPARA is required for increased expression of hlh-30/TFEB during infection." (PMID 33978570, 2021). "Infection further increased reporter expression throughout the body in nhr-49/PPARA gain-of-function mutants, becoming much stronger than wild-type animals." (PMID 33978570, 2021).